CD163 (CD163 molecule)
Diseases named in the same sentence as CD163 in open-access papers (continued):
Sharing a sentence is not in itself a finding about the gene and the disease.
diffuse large B-cell lymphoma (14 papers, 2017 to 2025). "Similar to other hematological malignancies, CD163+ TAMs are linked to poor prognosis in diffuse large B-cell lymphoma (DLBCL), follicular lymphoma (FL), cutaneous T-cell lymphoma (CTCL) and splenic marginal zone lymphoma (SMZL)." (PMID 38779660, 2024). "Interestingly, the CD163-positive monocytes population expressing PD-L1 was more elevated in HL patients compared to diffuse large B-cell lymphoma (DLBCL)." (PMID 34298810, 2021). "In this study, we found that serum-soluble CD163 may serve as a novel prognostic indicator in patients with Diffuse Large B-cell Lymphoma (DLBCL)." (PMID 38474108, 2024). "Importantly, macrophages expressing high levels of CD163 and CD86 have been observed in diffuse large B cell lymphoma, suggesting that the NLC phenotype may be seen in other B-cell malignancies and that AHCC may be effective there as well." (PMID 38140397, 2023). "In mice with diffuse large B-cell lymphoma (DLBCL) that were treated with CHOP and R-CHOP (addition of rituximab to standard CHOP therapy), the proportion of CD163+ macrophages were lower after both treatments, indicating a repolarization of M2-like macrophages to M1-like with these regimens." (PMID 38566987, 2024). "Furthermore, the activation of PD-L1/PD-L2 expressing CD163+TAMs “resets” CD3-CD56hiCD16-ve NK cell activation that mediates antibody-dependent cell-mediated cytotoxicity (ADCC) in Hodgkin lymphoma (CHL) and diffuse large B-cell Lymphoma (DLBCL) with doxorubicin (DOX)-based therapy." (PMID 36359776, 2022). "used a customized panel of 36 antibodies for DSP from samples of diffuse large B-cell lymphoma (DLBCL) patients pretreated with chemoimmunotherapy and revealed that CD68+CD163+ M2 macrophages showed dramatic negative impacts on prognosis." (PMID 36389765, 2022).
head and neck squamous cell carcinoma (14 papers, 2020 to 2025). A squamous cell carcinoma that arises from any of the following anatomic sites: lip and oral cavity, nasal cavity, paranasal sinuses, pharynx, larynx, and salivary glands. "A meta-analysis of the correlation between head and neck squamous cell carcinoma and TAMs revealed a significant association between decreased CD163+ TAM infiltration and favorable overall survival." (PMID 39068492, 2024). "On the other hand, the presence of CD163+ TAMs in the tumor infiltrate of head and neck squamous cell carcinoma (HNSCC) appears to be associated with metastasis and poor patient survival." (PMID 36831348, 2023). "In head and neck squamous cell carcinoma (HNSCC), the high levels of Notch1 receptors are associated with the high infiltration of CD163+ tumor-associated macrophages." (PMID 37512088, 2023). "In addition, LAG-3 expression closely correlated with CD163 in primary head and neck squamous cell carcinoma." (PMID 32756500, 2020). "Recently, overexpression of M2-like CD163+ TAMs in head and neck squamous cell carcinoma (HNSCC) patients, revealed a poor clinical prognosis in both overall survival (OS) and progression-free survival (PFS)." (PMID 37397243, 2023). "An additional study showed a prognostic significance between CD68+ and CD163+ in head and neck squamous cell carcinoma, and they found that CD68+ has no prognosis in patients, whereas CD163+ predicts poor prognosis." (PMID 36982316, 2023). "In head and neck squamous cell carcinoma (HNSCC), there is a significant positive correlation between the expression of FOXP3 mRNA and CD163 mRNA and TEV-PD-L1 features." (PMID 38087360, 2023).
macrophage activation syndrome (14 papers, 2015 to 2024). A complication of rheumatic disease that is caused by excessive activation and uncontrolled proliferation of T lymphocytes and well-differentiated macrophages. "Soluble CD163, a marker associated with macrophage activation syndrome, is elevated in some patients with Ebola virus disease." (PMID 39635525, 2024). "Many inflammatory disorders were associated with the elevated plasma levels of CD163, such as hemophagocytosis and the associated macrophage activation syndrome." (PMID 36428509, 2022). "CD163, a hallmark of macrophage activation, is highly expressed in macrophages of patients with active sJIA or macrophage activation syndrome (MAS)." (PMID 33076506, 2020). "Additionally, the soluble form of CD163, associated with macrophage activation syndrome, is known to be elevated in human cases of Ebola virus disease and Sudan virus disease, including severe or fatal infections." (PMID 39635525, 2024). "While macrophages were not specifically segmented in the GeoMx analysis of the lung, this upregulation indicates that pulmonary macrophages may be yet another source of soluble CD163, associated with macrophage activation syndrome." (PMID 39635525, 2024). "It was also reported that soluble CD163 in sera, one of the M2 markers, could be a diagnostic marker for macrophage activation syndrome in juvenile inflammatory arthritis." (PMID 29375576, 2017). "Hepatic macrophages in the EBOV-infected group demonstrated a mixed inflammatory/non-inflammatory profile, with upregulation of CD163 protein expression, associated with macrophage activation syndrome." (PMID 39635525, 2024). "CD163 may be produced to address overwhelming inflammatory reaction by macrophage activation syndrome in juvenile inflammatory arthritis." (PMID 29375576, 2017). "Robust CD163+ macrophage responses are also observed in macrophage activation syndrome (MAS, also referred to as hemophagocytic lymphohistioctyosis), an exaggerated systemic macrophage response observed in numerous neoplastic, autoimmune, and infectious diseases, including trypanosomiasis in cattle." (PMID 27195791, 2016). "So, it can be inferred that while SoJIA is active, or macrophage activation syndrome (MAS) is occurring, the macrophages increase expressing CD163, that maybe lead to the elevation of serum free iron levels, then to activate neutrophils to release NETs, that lead to increase histone level in serum." (PMID 30642364, 2019).
multiple myeloma (14 papers, 2017 to 2025). "In multiple myeloma (MM), high infiltration of CD163-positive TAMs has been significantly associated with poorer outcomes and lower complete response rates, with CD163 confirmed as an independent prognostic factor." (PMID 41239536, 2025). "In particular, the CD163+ subpopulation of TAMs has been recognized to infiltrate the BM niche, indicating poor prognosis in myeloma, while elevated levels of CD163+ macrophages were also detected in other hematologic and solid cancers." (PMID 40136679, 2025). "Lastly, we have evaluated the distribution of CD163 fractions in multiple myeloma in which we observed an increased fraction of EV-CD163 in newly diagnosed multiple myeloma patients compared to patients with relapse and in remission." (PMID 32397365, 2020). "The frequency of CD163+ M2-like MØs has been reported to be notably increased in acute and chronic myeloid leukaemia, chronic lymphocytic leukaemia, multiple myeloma and also adult ALL." (PMID 31337120, 2019). "Besides dysfunctional CD8+ T-cells, tumor-associated macrophages (CD68+, CD163+, CD86−) and inactivated DCs (CD58−) are also found co-localized with myeloma cells, participating as well in the orchestration of an immunosuppressive state." (PMID 40227595, 2025). "CD163-expressing TAMs displayed elevated levels of pSTAT3 and correlated to poor prognosis in 77 patients with myeloma from STAT3 is over-activated within CD163pos bone marrow macrophages in both Multiple Myeloma and the benign pre-condition MGUS." (PMID 36686729, 2022). "Except for total CD163+ monocyte populations, that did not increase further post-ASCT in AL amyloidosis, all other differences noted were common between AL and MM and most reached statistical significance." (PMID 31462637, 2019).
multiple sclerosis (14 papers, 2014 to 2024). A progressive autoimmune disorder affecting the central nervous system resulting in demyelination. "Increased CD163 expression has been linked to neuroinflammatory disease states such as multiple sclerosis, Alzheimer’s disease) HIV-associated neurocognitive disorders and schizophrenia." (PMID 25822971, 2015). "There is also evidence for accumulation of CD163+ macrophages in multiple sclerosis brains and in the lesions of traumatic brain injury." (PMID 35844224, 2022). "In agreement with previous findings in a mouse model of multiple sclerosis, our results therefore suggest that dysregulation of CD163, CD206 and IL-10 impacts the resolution of organ-specific inflammation." (PMID 29324769, 2018). "Soluble CD163 (sCD163) is a macrophage specific protein known to be up-regulated in serum from patients with multiple sclerosis (MS)." (PMID 24886843, 2014). "Foamy macrophages and microglia in the brain parenchyma have previously been found to express CD163 in HIV-encephalitis, multiple sclerosis, and head injury tissue." (PMID 24528486, 2014). "CD163 has an immunoregulatory function, and has been found in the parenchyma in other inflammatory diseases e.g. HIV-encephalitis and multiple sclerosis." (PMID 24528486, 2014). "However, CD163 is also expressed in the microglia in various nervous system diseases, such as AD, Parkinson’s disease (PD), HIV-encephalitis, multiple sclerosis, and head injury tissue." (PMID 38396970, 2024).
Parkinson disease (14 papers, 2014 to 2025). A progressive degenerative disorder of the central nervous system characterized by loss of dopamine producing neurons in the substantia nigra and the presence of Lewy bodies in the substantia nigra and locus coeruleus. "Targeting dexamethasone to CD163+ macrophages entails a neuroprotective effect in the substantia nigra in the rat 6-OHDA-induced disease model of Parkinson’s disease." (PMID 32752088, 2020). "There is a link between upregulation of CD163 and shorter disease course in Parkinson disease, while its overexpression results in a decrease in inflammation." (PMID 32686718, 2020). "In Parkinson disease rat models, delivery of CD163-targeted liposomes containing DEXA provided protection against 6-OHDA-induced dopaminergic neurodegeneration, which correlated with a distinctive microglia response." (PMID 29987742, 2019). "Other research showed that infiltrated CD163+ macrophages in brains from a Parkinson’s disease model modulate local microglia to promote neuroprotection." (PMID 30967783, 2019). "Further analysis of the signaling pathways involving CD163, FPR1, and VSIG4 revealed that CD163 was enriched in 76 pathways, including ribosome, Parkinson’s disease, leishmania infection, Fc gamma R-mediated phagocytosis, and B cell receptor signaling." (PMID 40630963, 2025). "Targeting dexamethasone to CD163+ macrophages has shown to be effective in limiting NASH progression and limiting 6-hydroxydopamine (6-OHDA)-induced Parkinson’s disease in rats." (PMID 32752088, 2020).
schizophrenia (14 papers, 2015 to 2026). A major psychotic disorder characterized by abnormalities in the perception or expression of reality. "Neurogenesis occurs in ependymal cells and this process is impaired in schizophrenia in association with elevated PVM cell CD163 expression." (PMID 37850104, 2023). "Indeed, we recently found elevated mRNA and protein levels of the macrophage marker CD163 in the brains of people with schizophrenia, and this increase was associated with changes in endothelial gene expression." (PMID 35844224, 2022). "Immunohistochemistry validated an increased density of CD163- positive perivascular macrophages in schizophrenia." (PMID 38704390, 2024). "A recent study identified increased presence of CD163 perivascular macrophages in the frontal cortex of schizophrenia patients." (PMID 37850104, 2023). "Macrophages play a major role in innate immunity in the brain and macrophage CD163 mRNA levels were found to be increased in schizophrenia patients, particularly in the high inflammation schizophrenia subgroup." (PMID 37841288, 2023). "There were two macrophage marker changes that demonstrated a clear elevation in high inflammation schizophrenia compared to high inflammation controls, and one was the macrophage scavenger receptor CD163 mRNA and the other was M1 macrophage marker FcγR1/CD64." (PMID 35844224, 2022). "Conversely, macrophage CD163 mRNA levels were increased in patients, substantially so in the high inflammation schizophrenia subgroup compared to low inflammation subgroup (>250%, p < 0.0001)." (PMID 35844224, 2022). "Conversely, immunohistochemical staining and in situ hybridization showed increased expression of inflammation-related genes associated with schizophrenia, such as HP, S100A9, CD163, and IFITM, in hippocampal and cortical blood vessels." (PMID 36192459, 2022). "In perivascular spaces, and subependymal zone, CD163+ cells are found in significantly higher amounts in patients with schizophrenia than in healthy donors." (PMID 35546942, 2022). "Further, circulating macrophages can enter the brain under conditions of neuroinflammation, and we found parenchymal and perivascular CD163+ macrophages were increased in density in the high inflammation subgroup of schizophrenia patients." (PMID 35844224, 2022). "Perivascular macrophages (CD163+) have been identified in the brain parenchyma of patients in about 40% of cases of schizophrenia with “severe inflammation”." (PMID 35546942, 2022). "A previous study which examines the same cohort of schizophrenia and control subjects found an increase in CD163 + cell number in the midbrain that was exaggerated in the high-inflammation schizophrenia group." (PMID 35841099, 2022). "In the SEZ, CD163+ macrophages are found in close proximity to neural stem and neuronal progenitor cells, and their density is increased in schizophrenia compared to controls and bipolar disorder." (PMID 34911938, 2021). "When comparing by diagnosis alone, CD163 mRNA was increased by 255.7% (F = 25.31, df = 49,1, p < 0.001) in schizophrenia cases relative to controls." (PMID 33133060, 2020). "CD163+ cells were found in the midbrain in proximity to melanin-containing dopaminergic neurons in both control and schizophrenia cases." (PMID 33133060, 2020). "When we tested if there was an increase in CD163+ cell density, we found a statistically significant increase in density of cells consistent with macrophages in people with schizophrenia compared to controls (t = 1.71, df = 52, p = 0.047)." (PMID 33133060, 2020). "Screening the gyrus rectus of the ventral medial prefrontal cortex for CD163 immunoreactive cells, we found these cells were predominately localised to blood vessels in every schizophrenia and control case examined (n = 76)." (PMID 30214039, 2020). "The relationship between gene expression of C1qA and CD163 reflected a pattern distinct to the high inflammatory/schizophrenia subgroup." (PMID 33133060, 2020).
schizophrenia (continued). "CD163+ perivascular macrophages were identified by immunohistochemistry in brain parenchyma in over 40% of “high inflammation” schizophrenia brains." (PMID 30214039, 2020). "Further, ICAM1 transcript levels were correlated with CD163 mRNA in the whole cohort (r = 0.42, p = 0.001) and also in the schizophrenia (r = 0.37, p = 0.036) and control (r = 0.40, p = 0.022) groups." (PMID 30214039, 2020). "The particularly strong positive correlation between CD59 and CD163 transcripts in the schizophrenia cases indicates that macrophages are most likely protected from complement-induced damage." (PMID 33133060, 2020). "In this regard, we have evidence that elevated CD163 transcripts, protein, and cell densities are some of the most robust and specific changes in high-inflammation schizophrenia in multiple brain regions, including the dorsolateral PFC, midbrain, and subependymal zone." (PMID 41567988, 2026). "Though CD163 is often used as a macrophage marker, it cannot reliably differentiate between macrophage phenotypes and is thus not useful in distinguishing macrophage type changes in high inflammation schizophrenia." (PMID 35844224, 2022). "Our anatomical scope of analysis is restricted as we used 14 μm tissue sections and sampled only a small part (rostro-caudally) of the gyrus rectus microscopically and thus, we cannot comment on the total number of CD163+ cells in the brains of people with schizophrenia." (PMID 30214039, 2020). "Inflammation related genes including S100A8, S100A9 and CHI3L1 are elevated in the hippocampus in schizophrenia and perivascular macrophages (CD163+) have been identified in the lumen of blood vessels and surrounding the endothelial cells in at least one schizophrenia hippocampus." (PMID 30214039, 2020). "Further, we have identified CD163+ macrophages in the parenchyma of some schizophrenia brains." (PMID 30214039, 2020). "Immunohistochemistry experiments revealed that the macrophage scavenger receptor CD163 could contribute to neuropathological changes in “high inflammation” schizophrenia brains." (PMID 33718116, 2020). "While we found positive correlations between complement transcripts (C1qA and C3) and microglia or astrocyte markers across diagnostic and inflammatory subgroups, the only unique strong positive correlation was between CD163 and C1qA mRNAs in schizophrenia cases with high inflammation." (PMID 33133060, 2020). "Therefore, we measured multiple microglial markers including TSPO and macrophage marker CD163 mRNA levels to compare the molecular phenotypes of microglia and macrophages between schizophrenia and normal controls as well as between high and low inflammation subgroups." (PMID 35844224, 2022). "However, we found that the high inflammatory/schizophrenia subgroup had a significant (89.6 and 74.3%) increase in CD163 protein levels compared to the low inflammatory/schizophrenia and control subgroups, respectively (F = 4.65, df = 46, 2, p = 0.014, both comparisons p < 0.05)." (PMID 33133060, 2020). "In support of our hypothesis, we saw increased gene expression and protein levels of the macrophage marker, CD163, in the region containing the dopamine cell bodies in schizophrenia, and these measures were most robustly increased in the schizophrenia cases with a high inflammatory biotype." (PMID 33133060, 2020). "Whereas, the macrophage marker CD163 mRNAs (log2FC = 0.35, FDR = 5.93E-04) was increased specifically in schizophrenia." (PMID 35844224, 2022). "Like the macrophage marker, CD163/CD64, this macrophage chemoattractant was significantly increased in the high inflammation schizophrenia subgroup relative to all other subgroups." (PMID 35844224, 2022). "We previously reported increases in CD163 and CD64 mRNAs in schizophrenia compared to controls and bipolar disorder; however, expression of no other peripheral immune cell markers or ICAM1 differed across diagnosis." (PMID 34911938, 2021).